CCR4 (C-C motif chemokine receptor 4)
Diseases named in the same sentence as CCR4 in open-access papers (continued):
Sharing a sentence is not in itself a finding about the gene and the disease.
COVID-19 (continued). "In severe COVID-19 patients, the frequencies of CCR6+cTfh cells and CCR4+cTfh cells were expanded, but CCR3+cTfh cells and Th1 cells were low in severe COVID-19 patients compared to healthy individuals." (PMID 34603308, 2021). "Some groups also reported that CCR4 supports the generation of short-lived effector CD8 T-cells and that there is a significant correlation between CCR4 expression on CD8 T-cells and their increased effector differentiation in HIV-negative adults with severe COVID-19." (PMID 36851789, 2023). "In addition, flow cytometric analysis of a blood sample from this COVID-19 patient revealed that CD4 and CD8 T-cells were hyperactivated and proinflammatory CCR4+ CCR6+ Th17 in CD4 T-cells markedly increased." (PMID 34676126, 2020). "Although decreased blood lymphocyte count of COVID-19 patients has been widely reported, lymphocytes were shown to be activated as the increases in the expression of HLA-DR in CD4+ and CD8+ cells, the percentage of CD4+ CCR4+ CCR6+ Th17 cells." (PMID 32733921, 2020). "The minimum level of Th17 was observed in patients with severe COVID-19, moreover, within the framework of the general pool of CCR6+ Th17, it was exactly noted in severe patients that there was a decrease in the proportion of CCR4− CXCR3+ Th17.1 cells and an increase in CCR4+ CXCR3—“classical” Th17." (PMID 36674665, 2023). "We also identified elevated CCR4 levels on transitional memory CD4+ and CD8+ T cells in these individuals highlighting that enhanced homing of T cells to the lung might exacerbate COVID-19." (PMID 36433939, 2022). "Drugs that inhibit CCR4 in absence of QT prolongation, such as mogalizumab, may serve as viable alternatives to hydroxychloroquine in the treatment of patients with severe COVID-19 manifestations." (PMID 32973504, 2020). "Similar percentages of CD4+ T cells expressing CCR4, CCR6, CD161, CXCR3, TBET, and GATA3 were found among healthy donors and pregnant women with or without COVID-19." (PMID 34326336, 2021).
psoriasis (25 papers, 2011 to 2025). An autoimmune condition characterized by red, well-delineated plaques with silvery scales that are usually on the extensor surfaces and scalp. "CD8 T cell subsets at various stages of cell differentiation exhibit selective/shifted expression of CCR4 and other skin-tropic chemokines associated with systemic and/or cutaneous inflammation in psoriasis." (PMID 40391222, 2025). "CCR4+ memory T cells could therefore represent a recirculating population responsible for systemic manifestations associated with severe psoriasis." (PMID 37958689, 2023). "In conclusion, these results hint at possible differences in the expression of receptors associated with tissue homing in CD8 T cells, namely CXCR3 and CCR4, from patients with mild-to-moderate psoriasis compared to healthy controls." (PMID 40391222, 2025). "Under homeostatic conditions, the skin homing capacity of circulating T cells is tightly regulated, whilst chronic skin conditions such as psoriasis are characterized by infiltrating T cells with markedly increased levels of CCR4 and CLA expression." (PMID 37006246, 2023). "CCR4−/− mice showed significantly decreased psoriasis-like inflammation compared to wild-type mice due to the reduced infiltrating TH17 in the psoriasis skin lesions and during the draining of the LN." (PMID 34831296, 2021). "From our previous data on psoriasis patients, CCR4+ memory T cells emerged as a putative recirculating population between skin and blood." (PMID 32318062, 2020). "In psoriasis, circulating CCR4 + CD4+ T cells significantly correlate with disease severity (PASI), and a strong negative correlation has been found for CCR5+ CD4+ T cells." (PMID 31963581, 2020). "In a previous study, in psoriasis patients, we found that circulating CCR4+ CD8+ TEMRA expressing CD103 correlated with both systemic inflammation and the severity of cutaneous psoriasis." (PMID 31350460, 2019). "The gene expression of CCR4 in the peripheral blood mononuclear cells (PBMCs) of psoriasis patients was detected by quantitative real-time PCR (qRT-PCR)." (PMID 29066845, 2017). "Chemokine-like factor 1 (CKLF1), a human cytokine that is a functional ligand for CCR4, displays chemotactic activities in a wide spectrum of leukocytes and plays an important role in psoriasis development." (PMID 29066845, 2017). "We found a significant up-regulation of CCR4 mRNA in the PBMCs of psoriasis patients compared with healthy individuals." (PMID 29066845, 2017). "In the present study, the results showed that both CKLF1 and CCR4 were highly expressed in the skin lesion from the patients with psoriasis." (PMID 25915746, 2015). "The proportion of CD8+CCR4+ T cells is increased in the peripheral blood of patients with psoriasis and palmoplantar pustulosis, and CD8+CCR4+ T cells effectively produce IL-4, IFN-γ, IL-2, and TNF-α." (PMID 21483764, 2011). "Together with CCR4, it is involved in mediating lymphocytes to cross vascular endothelial cells, and is significantly expressed in the lesions of inflammatory skin diseases such as human AD, contact dermatitis, and psoriasis." (PMID 40040698, 2025). "However, CCR4 was expressed at a higher frequency in the CD8 MAIT cell compartment in psoriasis than in healthy subjects." (PMID 40391222, 2025). "CCR4+ CLA+ cells have previously been found in psoriasis skin lesions." (PMID 37131254, 2023). "Moreover, ligands for CCR4—CCL17 and CCL22, and CCR10—CCL27 have been associated with AD, psoriasis, cutaneous lymphomas, and systemic sclerosis." (PMID 37371632, 2023). "CCR4 plays a role in psoriasis development via the regulation of Th17 cells." (PMID 34831296, 2021). "In addition, CLA+ CD4+ TCM cells expressing CCR6+ or CCR4+ CXCR3+ negatively correlated with the severity of psoriasis." (PMID 31963581, 2020).
psoriasis (continued). "However, the comparison of the phenotype of circulating CD8+ T cells between psoriasis patients and healthy subjects evidenced a significant increase in the percentage of CCR4+CXCR3+ CD8+ TCM cells in the circulation of psoriasis patients." (PMID 32318062, 2020). "By contrast, we observed increased circulating percentage of CCR4+ T cells in psoriasis patients." (PMID 27595115, 2016). "We have recently reported that CCR4+ CD4+ T cells are increased in the circulation of patients with psoriasis proportionally with the increased severity of the cutaneous manifestations of the disease expressed as PASI (Psoriasis Area and Severity Index) score." (PMID 27595115, 2016). "Notably, psoriasis arthritis may be distinguished from skin‐confined psoriasis by the presence of CLA+CCR4+CCR10+ T cells in peripheral blood, suggesting migration of pathogenic T‐cell clones across tissue compartments." (PMID 37144705, 2023). "However, patients showed an expanded circulating population of CD8+ TCM cells with phenotype CCR4+CXCR3+ that could play a role in the pathophysiology of psoriasis and possibly in disease recurrence." (PMID 32318062, 2020). "This has been observed in different studies, evidencing a correlation between CCR4+ CCR5+ CD8 TEFF with serum level of C-reactive protein (CRP) and with (psoriasis area and severity index) PASI score in patients with psoriatic disease." (PMID 37958689, 2023). "The role of CCR4, CCR8, CCR10, and CCR6 or their ligands has been proposed in atopic dermatitis (AD), psoriasis, cutaneous lupus erythematosus, systemic sclerosis, or malignant skin tumors, but not in CU." (PMID 37371632, 2023). "IL-17 therapeutic blockade decreased CD3+CD4+CCR6+, CD3+CD4+CXCR3+, CD3+CD4+CCR6-CXCR3+(Th1), CD3+CD4+CCR6+CCR4+(Th17), CD3+CD4+CCR6+CCR4+CXCR3+(CXCR3+-Th17), and CD3+CD4+CCR6+CCR4-CXCR3+(Th17.1) cell populations in responding psoriasis patients." (PMID 35925616, 2022). "Using multiparameter flow cytometry we examined T-cell subpopulations characterized by CCR6, CCR4, and CXCR3 chemokine receptor surface expression at baseline and after initiation of biologic therapy in PBMCs collected from 30 psoriasis patients." (PMID 35925616, 2022). "CCR4-expressing CCR7+ TEM have been reported in inflamed peripheral tissues (for example, in psoriasis and juvenile idiopathic arthritis)." (PMID 22490506, 2012). "Psoriasis patients without arthralgia showed lower numbers of CCR6-CXCR3+CCR4+ cells and higher numbers of CCR6+ DN cells." (PMID 35045868, 2022). "Recent study indicated that CCR4 and CXCR3 may participate in psoriasis recurrence or redistribution to distant sites." (PMID 34012433, 2021). "Taken together, CCR4 and CCR6 are important for the pathogenesis of psoriasis." (PMID 34831296, 2021). "In immunopathological skin conditions such as psoriasis, the expanded subset of TCM cells expressing CCR4 and CXCR3 could play a role in disease recurrence or redistribution to distant sites such as joint synovial tissues and enthesis." (PMID 32318062, 2020). "Few studies have demonstrated that CD4+ TCM cells are significantly increased in patients with psoriasis 10 while circulating CLA+CCR4+CD8+ TCM cells are also expanded in the patients 11, indicating that TCM cells may be involved in the pathogenesis of psoriasis." (PMID 32929360, 2020).
atopic dermatitis (24 papers, 2004 to 2025). "Along with its ligands, CCR4 has been associated to the pathophysiology of allergic skin illnesses including atopic dermatitis (AD), where elevated blood levels of CCL17 are linked to disease activity." (PMID 37259456, 2023). "Studies using murine atopic dermatitis models showed that CCR4 deficiency or the use of a CCR4 antagonist ameliorated allergic responses." (PMID 36555280, 2022). "The discovery by Campbell and colleagues that skin-homing cutaneous lymphocyte antigen (CLA)+ T cells express high levels of CCR4 expression, implicated the receptor in the pathology of atopic dermatitis." (PMID 25981299, 2015). "Several association studies using genetic variants of genes CCL17 and CCR4 in the CCR4 pathway have been conducted to discover genetic components in the pathogenesis of atopic dermatitis." (PMID 22125604, 2011). "CCR4 has long been regarded as a potential therapeutic target for allergic diseases such as atopic dermatitis and bronchial asthma." (PMID 34771703, 2021). "Together with CCL22, which showed a 24-fold overexpression in CD11b+CD11c+ MDSCs, both chemokines are known to attract CCR4-bearing Th2 cells and serve as markers for the severity of Th2-mediated atopic dermatitis." (PMID 34721430, 2021). "Because CCR4 is preferentially expressed on Th2 cells, TARC has been associated with Th2-dominant skin diseases, including atopic dermatitis, bullous pemphigoid, and cutaneous T-cell lymphoma." (PMID 33572144, 2021). "For instance, TARC recruits CCR4+ Th2 cells into lesional skin in atopic dermatitis, where serum TARC levels are used as a sensitive biomarker for monitoring disease activity." (PMID 33572144, 2021). "This study investigated the influence of 0.00584% hydrocortisone aceponate spray (HCA; Cortavance Virbac SA, Carros, France) on blood serum cortisol levels and peripheral blood CCR4+ CD4+ T-lymphocyte levels in dogs with atopic dermatitis." (PMID 26464935, 2014). "Analysis by immunohistochemistry of airway mucosa of people with atopic asthma after antigen challenge revealed that large numbers of CCR4+ and CCR8+ T cells express IL-4, and CCR4 expression was prominent in people with severe atopic dermatitis, which decreased upon abatement of disease activity." (PMID 15526056, 2004). "This was subsequently supported by a study in which the levels of both CCR4 and CLA were shown to be increased on the surface of peripheral blood CD4+ T cells from severe atopic dermatitis subjects compared with control subjects." (PMID 25981299, 2015). "By contrast, atopic dermatitis and Th2-related genes, including Il4, Il5, Il13 and Il31 were lowly expressed or not detected at all, and other atopic dermatitis-related transcripts (Ccr4, Ccl17, Ccl24) were not significantly differentially expressed." (PMID 38528069, 2024). "CCL17 was involved in the process of pulmonary fibrosis through CCR4-positive alveolar lymphocytes and macrophages, and the level of CCL17 correlated positively with disease activity and was used as a biomarker for monitoring the severity of atopic dermatitis." (PMID 34943853, 2021). "Chemokine receptors such as chemokine (C-C motif) receptor 4 (CCR4) or CCR8 have been studied in skin diseases, e.g., atopic dermatitis, but not in CU." (PMID 37371632, 2023). "Similarly, CCR4-involving cell-cell communication, with the ligands CCL5, CCL17, CCL22, also showed diseased organ specificity, but in nonlesional atopic dermatitis and psoriatic skin." (PMID 40809141, 2024).
T-cell lymphomas (24 papers, 2013 to 2025). "CCR4 (+) T-cell lymphomas are associated with a poorer prognosis, possibly because of downregulation of T-cell mediated antitumor host response." (PMID 25355407, 2014). "The generated anti-CCR4 human antibodies demonstrated ADCC-dependent therapeutic anti-tumor effect in vivo in the T-cell deficient nude mice bearing the xenografted human T-cell lymphoma." (PMID 25080123, 2014). "Therefore, CCR4 has a pathogenic role in selected T-cell NHL and has been the subject of ongoing investigations with the anti-CCR4 monoclonal antibody mogamulizumab." (PMID 28031823, 2016). "Mogamulizumab is an anti-CCR4 mAb that has been approved for the treatment of T-cell lymphomas mycosis fungoides and Sézary syndrome, two of the most common T-cell lymphomas." (PMID 39982274, 2025). "Mogamulizumab, which is a humanized anti-CCR4, exhibits potent clinical efficacy against CCR4-positive CTCLs and other T cell lymphomas and was shown to efficiently decrease Tregs, leading to CTCL growth inhibition." (PMID 39409988, 2024). "Utilizing this foundational technique, CAR-T trials targeting CD3, CD5, CD7, TRBC1, and CCR4 are ongoing and possess immense potential in the treatment of T-cell lymphomas." (PMID 39456582, 2024). "Mogamulizumab is a humanized IgG1 mAb targeting chemokine receptor 4 (CCR4), which is expressed in many T-cell lymphomas as well as most Th2 and regulatory T-cells." (PMID 39456582, 2024). "Mogamulizumab, a defossilized humanized anti-CCR4 monoclonal antibody, has been shown to effectively treat T-cell lymphomas by enhancing antibody-dependent cell-mediated cytotoxicity (ADCC)." (PMID 38915099, 2024). "The other two defucosylated mAbs approved for clinical application are mogamulizumab, an anti-CCR4 antibody used for T cell lymphoma, and benralizumab, an anti-IL-5R antibody used for severe eosinophilic asthma." (PMID 34070311, 2021). "Mogamulizumab (Moga), an antibody targeting anti-CC-chemokine receptor 4 (CCR4), eliminates CCR4+ cells in T cell malignancies, depletes a subset of high expressing CCR4+ Tregs, and is approved to treat CCR4+ T cell lymphomas in Japan." (PMID 30400835, 2018). "The humanized anti-CCR4 antibody mogamulizumab has demonstrated a high potential for treatment of CCR4-positive T-cell lymphomas." (PMID 29099057, 2017). "ATL can often be distinguished from other T-cell lymphomas by its strong uniform expression of CD25/C-C chemokine receptor type 4 (CCR4)." (PMID 26610571, 2015). "Using a panel of 24 adult adult T cell lymphoma patients, the vast majority of PBMCs from these subjects (22/24) were shown to express CCR4 by PCR and to respond to CCL17 and CCL22 in chemotaxis assays." (PMID 25981299, 2015). "In a phase 1 trial of 16 patients with R/R CCR4(+) mature T-cell lymphomas, 31% (n = 5) achieved a response (CR: 13%; n = 2)." (PMID 25355407, 2014). "In a mouse model of human T-cell lymphoma, significant survival benefit was demonstrated for animals treated with the newly selected anti-CCR4 antibodies." (PMID 25080123, 2014). "The anti-CCR4 antibody, mogamulizumab, has been tested in clinical studies, although the study population for this was patients with relapsed CCR4+ adult T-cell lymphomas and other peripheral T-cell lymphomas." (PMID 23448278, 2013). "In addition to these, a notable range of CCR4 antagonists has been evaluated in clinical studies, although mogamulizumab remains the sole approved CCR4 antagonist in oncology, specifically indicated for the treatment of T cell lymphomas." (PMID 40134607, 2025). "CCR4 targeted by mogamulizumab depletes CCR4+ T cells to treat T-cell lymphomas." (PMID 40986007, 2025). "Consequently, CCR4 emerges as a promising therapeutic target, particularly in T-cell lymphomas like ATLL." (PMID 38396877, 2024).
T-cell lymphomas (continued). "Furthermore, an interesting approach based on CCR4 CAR-T cells displayed antigen-dependent potent cytotoxicity against patient-derived cell lines of T-cell lymphoma, thus suggesting the feasibility of such approach also for CCR4-expressing T-ALL patients." (PMID 36624522, 2023). "To verify the therapeutic potential of CCL2-CCR4 signaling in a solid tumor, in this study, we used Mogamulizumab, a humanized anti-CCR4 monoclonal antibody, a promising agent for CCR4-positive T-cell lymphomas, to treat subcutaneously implanted HNSCC tumor in nude mice." (PMID 35177591, 2022). "While CCR4 mAbs have primarily been studied in T-cell NHL, it has been hypothesized that influencing the tumor microenvironment by halting Treg trafficking through CCR4 blockade may be broadly beneficial in many cancers." (PMID 25355407, 2014). "This glycoengineered monoclonal antibody depletes CCR4-expressing cells by antibody-dependent cell-mediated cytotoxicity (ADCC), and has significant clinical activity in CCR4+ T-cell NHL." (PMID 28031823, 2016). "However, other reports assessing mogamulizumab for the treatment of T cell lymphoma have not demonstrated this correlation between CCR4 expression and clinical outcome." (PMID 41295262, 2025).